PPARG (peroxisome proliferator activated receptor gamma)
Diseases named in the same sentence as PPARG in open-access papers (continued):
Sharing a sentence is not in itself a finding about the gene and the disease.
cardiac hypertrophy (69 papers, 2008 to 2026). "Cardiomyocyte-specific PPARγ deficiency induces cardiac hypertrophy in mice, whereas overexpression of PPARγ in cardiomyocyte enhances cardiac uptake of lipids and glucose." (PMID 36998980, 2023). "Studies have shown that PPARA and PPARG are closely associated with the development of myocardial hypertrophy." (PMID 35281609, 2022). "Mice with specific knockout of PPARγ exhibited modest cardiac hypertrophy, while ectopically expressing PPARγ in heart tissues also appeared to cause cardiac hypertrophy, accompanied by glucose accumulation and mitochondrial structure disorder." (PMID 34305596, 2021). "Cardiac PPARγ activity has also been linked to cardiac hypertrophy, as cardiac-specific PPARγ deficient mice exhibit a robust increase in LV size/mass." (PMID 33041869, 2020). "Cardiomyocyte-specific PPARγ knockout mice were more susceptible to cardiac hypertrophy with systolic cardiac function." (PMID 32028670, 2020). "Conversely, cardiac-specific PPARγ overexpressing mice also demonstrate a robust cardiac hypertrophy, which is actually associated with elevations in mRNA expression of genes regulating fatty acid oxidation (e.g., CPT-1, acyl CoA oxidase)." (PMID 33041869, 2020). "It should be noted that cardiac hypertrophy in heart-specific PPARγ knockout mice associated with oxidative damage and mitochondrial dysfunction progresses with age and leads to dilated cardiomyopathy and premature death." (PMID 30400386, 2018). "The PPARG gene encoding PPARγ is upregulated in response to hypoxia through HIF-1α induction in cardiac hypertrophy." (PMID 27589734, 2016). "This is in agreement with other reports showing that cardiac PPARγ mRNA was reduced in ACE2-null mice associated with myocardial hypertrophy." (PMID 24067190, 2013). "For example, downregulation of PPARγ by an aberrant expression of miR-27b in cardiomyocytes was associated with cardiac hypertrophy in mice, whereas miR-27b-dependent PPARγ downregulation in macrophages favors the inflammatory response to LPS." (PMID 23024649, 2012). "Because generalized PPARγ gene deletion causes embryonic lethality, we examined the role of PPARγ in the development of cardiac hypertrophy in vivo using heterozygous PPARγ-deficient (PPARγ+/-) mice." (PMID 20814542, 2010). "QLQX has been found to improve cardiac hypertrophy by upregulating PPARγ and PGC-1α, reduce cardiomyocyte apoptosis caused by high-glucose environments, and prevent and treat heart failure through various mechanisms, including upregulation of PPARγ and downregulation of miRNA-22." (PMID 39095596, 2024). "Relevant studies have confirmed that PPARγ activation improved myocardial cell injury caused by ischemia/reperfusion, reduced myocardial fibrosis, reduced cardiomyocyte apoptosis, and inhibited cardiac hypertrophy." (PMID 37033616, 2023). "It is therefore that inhibition of FABP4 in human might show beneficial effects against heart hypertrophy and cardiac events associated with PPARγ agonist drugs." (PMID 27294862, 2016). "However, cardiac hypertrophy caused by mechanical overload can be inhibited by increasing the PPARγ levels with treatments of TZD drugs or 15-deoxy-Δ12,14-prostaglandin J2." (PMID 27047938, 2016). "In this respect it might be significant that rosiglitazone-induced myocardial hypertrophy, an early hallmark and important risk factor for the development of heart failure, still occurs in cardiomyocyte-specific PPARγ knock-out mice." (PMID 24938300, 2014). "This implies, that in case the pathological cardiac hypertrophy is induced through a PPARγ-dependent mechanism, it could be caused by 31 rosiglitazone-modulated genes." (PMID 24938300, 2014). "The PPARγ deficiency has been exhibited to develop cardiac hypertrophy in PPARγ-null mice." (PMID 24067190, 2013).
cardiac hypertrophy (continued). "Interestingly, when cardiomyocytes-specific PPARγ-overexpressing mice were crossed with PPARα-deficient mice, cardiac hypertrophy was significantly ameliorated, along with upregulated FAO and decreased apoptosis, reactive oxygen species (ROS) levels, and endoplasmic reticulum stress." (PMID 35185581, 2022). "Prior studies have used differential gene expression analysis to identify protein kinase A (PKA) and Peroxisome proliferator-activated receptor gamma (PPAR-γ) as important clusters to understand age and sex differences in cardiac hypertrophy." (PMID 40060665, 2025). "Peroxisome proliferator-activated receptor γ (PPARG), when activated by ligands, can inhibit ventricular hypertrophy, improve ventricular remodeling, and enhance cardiac function." (PMID 40552149, 2025). "Results from CRP treatment have indicated an upregulation of PPARγ expression levels, thereby inhibiting the progression of pathological cardiac hypertrophy." (PMID 38998484, 2024). "In summary, tangerine peel demonstrates significant potential in preventing and mitigating pathological cardiac hypertrophy by modulating the activation of PPARγ and inhibiting fibrosis." (PMID 38998484, 2024). "A key molecular mechanism involves the activation of PPARγ by tangerine peel, with Peroxisome Proliferator-Activated Receptors (PPARs) playing a crucial role in regulating cardiac metabolism and pathological cardiac hypertrophy." (PMID 38998484, 2024). "Cardiac-specific overexpression of miR-27b has been reported to increase pressure overload-induced cardiac hypertrophy via PPARG but attenuated angiotensin II-induced atrial fibrosis via ALK5." (PMID 37276142, 2023). "Mechanistically, we have demonstrated that peroxisome proliferator activated receptor γ (PPARγ) is the direct target of luteolin in the setting of pathological cardiac hypertrophy and the related metabolic disorders." (PMID 36998980, 2023). "Although the therapeutic outcomes of transgenic mice and rosiglitazone are ambiguous, there is increasing evidence that PPARγ is a protective modulator in cardiac hypertrophy and heart failure." (PMID 36998980, 2023). "Overall, these results indicate that GLPs inhibit cardiac hypertrophy through downregulating key genes for hypertrophy and fibrosis and attenuate pressure overload-induced pathological cardiac hypertrophy by activating PPARγ." (PMID 37033616, 2023). "Further in vitro and in vivo experiments verified that luteolin can significantly attenuate pathological cardiac hypertrophy and HF mainly by activating PPARγ pathway." (PMID 36998980, 2023). "Further research indicated that GLPs attenuated the mRNA levels of hypertrophic and fibrotic markers to inhibit cardiac hypertrophy through the PPARγ/PGC-1α pathway." (PMID 37033616, 2023). "Overall, our study demonstrates that GLPs can protect against pressure overload-induced cardiac hypertrophy through PPARγ activation." (PMID 37033616, 2023). "In summary, our results first revealed that luteolin prevents cardiac hypertrophy and HF by regulating myocardial fatty acid and glucose metabolism, which relies on PPARγ activation." (PMID 36998980, 2023). "Relevant studies in rats fed a high-fat diet have confirmed that metformin can attenuate cardiac hypertrophy via the PPARγ signaling pathway." (PMID 37033616, 2023). "In summary, we here found out from FDA-approved drug library that luteolin emerged as a therapeutic candidate for pathological cardiac hypertrophy and heart failure by directly suppressing ubiquitin-proteasomal degradation of PPARγ and metabolic homeostasis." (PMID 36998980, 2023). "PPARγ is a critical modulator against cardiac hypertrophy, and its agonists have been found to inhibit cardiomyocytes hypertrophy by improving metabolic homeostasis and inflammatory response." (PMID 36998980, 2023). "Other literature has reported that PPARγ signaling inhibits cardiac hypertrophy by activating autophagy." (PMID 37033616, 2023).
cardiac hypertrophy (continued). "Consistently, Pparγ knockdown abrogated the protective effect of luteolin on PE-induced expression of the relevant cardiac hypertrophy markers." (PMID 36998980, 2023). "While peroxisome proliferator-activated receptors (PPARs) are involved in energy metabolism and mitochondrial function-related genes, multiple studies have shown the important role of PPARγ in the cardiac hypertrophy." (PMID 37264260, 2023). "Our data clearly supported that luteolin is a promising therapeutic compound for pathological cardiac hypertrophy and heart failure by directly targeting ubiquitin-proteasomal degradation of PPARγ and the related metabolic homeostasis." (PMID 36998980, 2023). "While the PPARγ agonists haven't been able to be applied in clinic, our study demonstrated that the strategies of stabilizing PPARγ can be a key alternative way for pathological cardiac hypertrophy and HF treatment." (PMID 36998980, 2023). "After treatment with rosiglitazone, a PPARγ agonist, cardiomyocytes-specific PPARγ-null mice display serious cardiac hypertrophy and cardiac dysfunction, indicating the indirect hypertrophic effect of PPARγ agonists." (PMID 35185581, 2022). "The expression of PPARA and PPARG significantly downregulated in myocardial hypertrophy, and activation of either PPARA or PPARG was able to inhibit the hypertrophic response." (PMID 35281609, 2022). "Cardiomyocytes-specific knockout of PPARγ leads to mild cardiac hypertrophy with preserved heart function." (PMID 35185581, 2022). "In the cardioprotective effects of apigenin, previous studies reported that PPARα and PPARγ were involved in ameliorating cardiac hypertrophy and myocardial abnormality." (PMID 36092543, 2022). "During cardiovascular diseases, the activation of PPARγ reduces myocardial fibrosis and apoptosis, improves myocardial ischemia-reperfusion injury, and inhibits myocardial hypertrophy." (PMID 34422028, 2021). "The amelioration of decompensated myocardial hypertrophy induced by NOB was eliminated by PPARγ inhibitor administration, resulting in an enhanced HW/BW ratio." (PMID 34422028, 2021). "Hesperidin, a flavanone glycoside and a known PPARγ ligand, improved cardiac hypertrophy by improving cardiac hemodynamics, as well as inhibiting oxidative stress and apoptosis through increasing PPARγ expression." (PMID 32028670, 2020). "An increase in plasma adiponectin level by the administration of PPARγ agonist or adenoviral overexpression enhanced the therapeutic efficacy of hMSCs in the cardiac hypertrophy model." (PMID 32652045, 2020). "Similar to PPARα, heart-specific PPARγ knockout mice developed cardiac hypertrophy with preserved normal cardiac metabolism and function." (PMID 30400386, 2018). "Inconsistent with our study, agonist of PPARγ induced cardiac hypertrophy in both the wild type mice and cardiomyocyte-specific PPARγ knockout mice, implying that the in vivo effects of the agonist on the heart are mediated by non-PPAR effects." (PMID 27110236, 2016). "For example, both over-expressing and knock-out PPARγ in mice heart can induce lipid disorder and leads to cardiac hypertrophy." (PMID 27294862, 2016). "Studies later showed that PPARγ also expressed in rat cardiac myocytes and was closely involved in the process of cardiac hypertrophy." (PMID 27110236, 2016). "On the other hand, a study using cardiomyocyte-specific PPARγ knock-out mice indicated that rosiglitazone can promote the development of myocardial hypertrophy in a PPARγ -independent manner." (PMID 24938300, 2014). "Its role in heart remodeling is evidenced by findings that mice with a cardiomyocyte-specific knockout of PPARγ develop cardiac hypertrophy." (PMID 24667808, 2014). "The PPARγ antagonist GW9662 prevented the cardiac protective effects of irbesartan in mice with myocardial hypertrophy and interstitial fibrosis." (PMID 24067190, 2013).
cardiac hypertrophy (continued). "In contrast, treatment with irbesartan prevents ACE2 deficiency-mediated cardiac hypertrophy and myocardial ultrastructure injury in ACE2 mutant mice with elevation of the PPARγ level and suppression of the TGFβ−CTGF−ERK signaling." (PMID 24067190, 2013). "Recent studies have focused on ligands of PPARγ, for its actions on the myocardium, and other studies have suggested a role for PPARγ as an inhibitor of cardiac hypertrophy, that can decrease the NF-κB binding activity." (PMID 24171042, 2013). "Our findings indicated the protective effects of irbesartan on myocardial hypertrophy in ACE2KO mice via activation of the PPARγ signaling pathway." (PMID 24067190, 2013). "However, PPARγ has many other actions on cellular biology, including cell proliferation, differentiation, and apoptosis, which may cause therapeutic complications such as fluid retention, cardiac hypertrophy and failure, and potential carcinogenicity." (PMID 21664456, 2011). "Pressure overload-induced cardiac hypertrophy was more prominent in heterozygous PPARγ+/- mice than in wild-type (WT) mice." (PMID 20814542, 2010). "Treatment with pioglitazone strongly inhibited the pressure overload-induced cardiac hypertrophy in WT mice and moderately in PPARγ+/- mice." (PMID 20814542, 2010). "Previous studies demonstrated that PPARγ deficiency induced cardiac hypertrophy without interfering with cardiac contractile function." (PMID 38505620, 2024). "Therefore, the identification of potential PPARγ activators has great potential research value for the treatment of cardiac hypertrophy." (PMID 37033616, 2023). "Additionally, many traditional Chinese medicines have been shown to attenuate cardiac hypertrophy by upregulating PPARγ." (PMID 37033616, 2023). "PPARγ activation improves cardiac hypertrophy and cardiometabolic dysfunction." (PMID 37033616, 2023). "Combining the results of KEGG analysis with PDB data, we hypothesized that PPARγ may be a crucial target for luteolin in the inhibition of cardiac hypertrophy and HF." (PMID 36998980, 2023). "Cross analysis of large-scale transcriptomics and drug-target interacting investigations indicated that peroxisome proliferator activated receptor γ (PPARγ) was the direct target of luteolin in the setting of pathological cardiac hypertrophy and metabolic disorders." (PMID 36998980, 2023). "Notably, we first verified that luteolin can directly bind to PPARγ, a crucial regulator of metabolic homeostasis, prevents its ubiquitination mediated degradation, thereby exerts the protective effect against cardiac hypertrophy and heart failure." (PMID 36998980, 2023). "It was found that CRP could inhibit Ang II-induced myocardial hypertrophy in mice through upregulation of PPARG." (PMID 35281609, 2022). "The beneficial effects of NOB against decompensated cardiac hypertrophy were also reversed by the PPARγ inhibitor, as indicated by the enhanced ANP and BNP expression assessed by qRT-PCR and the enlarged cross-sectional area of cardiomyocytes revealed by HE and WGA staining." (PMID 34422028, 2021). "This study was to investigate whether pioglitazone (PIO), a PPARγ agonist, could protect against pressure overload-induced cardiac hypertrophy." (PMID 27110236, 2016). "Cardiomyocyte-specific PPARγ knockout mice could induce cardiac hypertrophy and activation of PPARγ by the specific agonist, rosiglitazone, can inhibit cardiac hypertrophy in vivo and in vitro." (PMID 27110236, 2016). "However, the role of PPARγ in the development of pathological cardiac hypertrophy and in mediating the effect of rosiglitazone thereupon is not entirely clear yet." (PMID 24938300, 2014). "In addition to PPARγ, in mouse models of cardiac hypertrophy and heart failure, the activation of PPARα has also been shown to cause noxious effects on the development of the ventricular function." (PMID 19173749, 2009).
cardiac hypertrophy (continued). "Thus, we speculated that PPARγ might be the direct target required for luteolin to exert a protective effect in cardiac hypertrophy and HF." (PMID 36998980, 2023). "Thus, GLPs protect against pressure overload-induced cardiac hypertrophy through PPARγ activation." (PMID 37033616, 2023). "In addition, the peroxisome proliferator-activated receptor γ (PPARγ) and HIF1α in human and mouse cardiac hypertrophy activated FAs uptake and GPL biosynthesis genes, and increased glucose-to-GPL conversion via G-3P pathway followed by changing myocardial metabolism and forming heart disease." (PMID 31316482, 2019). "Some animal studies have suggested that the direct action of PPARγ on the heart could be beneficial, since TZDs improve cardiac performance, decrease cardiac hypertrophy, and may also have beneficial effects on left ventricular remodeling and function after ischemic injury." (PMID 22745632, 2012). "The activation of peroxisome proliferator-activated receptors (gamma (PPARγ)) and its coactivator-1α (PGC-1α) play key roles in the amelioration of cardiac hypertrophy and dysfunction." (PMID 35370696, 2022). "Previous studies revealed that Ang II-induced cardiac hypertrophy is mediated by AMPK-, Sirt3-, and PPARγ- dependent mechanisms." (PMID 31636805, 2019). "However, cardiovascular diseases such as cardiac hypertrophy and cardiac overload are diseases in which the canonical WNT/β-catenin pathway is reduced and PPARγ is upregulated." (PMID 36902342, 2023). "Quercetin prevented cardiac hypertrophy via suppression of the activator protein 1 (AP1) transcription activity and promotion of the activation of peroxisome proliferator-activated receptor γ (PPARγ)." (PMID 33260783, 2020). "For example, cardiomyocyte-restricted PPARγ knockout mice develop cardiac hypertrophy, although presenting no changes in lipid metabolism genes." (PMID 25559887, 2015). "In this study, following finding luteolin prevents cardiac hypertrophy and heart failure via activating PPARγ pathway, and we also found that by binding to PPARγ luteolin interrupted the interaction between TRIM55 and PPARγ and prevents the TRIM55-mediated proteasome-dependent degradation of PPARγ." (PMID 36998980, 2023). "The cardiomyocyte-specific knockout of PPARγ induced cardiac hypertrophy, probably through the lack of inhibition of NF-κB, whereas the overexpression of PPARγ in cardiomyocytes resulted in cardiac myopathy characterized by increased lipid and glycogen storage and cardiac dysfunction." (PMID 36768666, 2023). "Researchers have not clearly determined whether excessively high or low PPARγ expression in cardiomyocytes induces cardiac hypertrophy and dysfunction." (PMID 35185581, 2022). "Rosiglitazone leads to cardiac hypertrophy partially independent of cardiomyocyte PPARγ." (PMID 32028670, 2020). "More importantly, treatment with irbesartan remarkably attenuated ACE2-dificiency induced myocardial hypertrophy and ultrastructure injury along with augmentation of cardiac PPARγ level, without having a differential effect on the expression of PPARα and PPARδ." (PMID 24067190, 2013). "Other studies, in contrast, have suggested that TZDs induce cardiac hypertrophy in rodent models of diabetes, although increased cardiac mass could not be attributed directly to PPARγ actions on the heart." (PMID 22745632, 2012). "Another study found that mice lacking PPARγ in cardiomyocytes exhibited mild cardiac hypertrophy." (PMID 18648539, 2008). "Although myocardin upregulation completely restored cardiac contractile function in Atp6v0d1AKO mice, the cardiac hypertrophy was ameliorated but not completely corrected, which may be attributed to the effect of PPARγ that was not counteracted by myocardin upregulation." (PMID 38505620, 2024).
cardiac hypertrophy (continued). "Reasons for these discrepancies are currently unknown, and surprisingly, deletion of PPARα alleviates the cardiac dysfunction present in cardiac-specific PPARγ overexpressing mice without impacting cardiac hypertrophy, yet actually increases myocardial fatty acid oxidation." (PMID 33041869, 2020).